IL27 (interleukin 27)
Diseases named in the same sentence as IL27 in open-access papers (continued):
Sharing a sentence is not in itself a finding about the gene and the disease.
psoriasis (22 papers, 2012 to 2025). An autoimmune condition characterized by red, well-delineated plaques with silvery scales that are usually on the extensor surfaces and scalp. "The elevated serum concentrations of IL-27, IL-30, and IL-33 have also been observed in psoriasis patients and are significantly associated with disease severity, as determined by the PASI." (PMID 40731810, 2025). "In line with the findings made in vitro, IL-27 treatment also disturbed lipid metabolism and restrained mitochondrial activity of dermal and splenic γδ T cells in mice with psoriasis." (PMID 38982043, 2024). "Expression of IL-27p28 was reduced in PBMCs of patients with psoriasis compared with healthy controls, and serum levels of IL-27 were reduced in patients with psoriasis." (PMID 38566992, 2024). "Injection of IL-27 into psoriasis mice upregulated serum levels of IFNγ and decreased serum levels of IL-17, but inhibition of IL-27 downregulated the expression of IFNγ and increased IL-17 expression." (PMID 38566992, 2024). "More importantly, we found that the downregulation of IL-27Ra on γδ T cells is involved in the pathogenesis of psoriatic inflammation and IL-27 has preventive and therapeutic effects in ameliorating psoriasis." (PMID 38982043, 2024). "This work uncovers the metabolic basis for the immune regulatory activity of IL-27 and provides novel insights into IL-27/IL-27Ra signaling, γδ T17 biology and the pathogenesis of psoriasis." (PMID 38982043, 2024). "In summary, this work uncovered the metabolic basis for the immune regulatory activity of IL-27 in restraining γδ T17 mediated inflammation, which provides novel insights into IL-27/IL-27Ra signaling, γδ T17 biology and the pathogenesis of psoriasis." (PMID 38982043, 2024). "Serum levels of IL-27 were elevated in patients with psoriasis compared to those in healthy controls, and serum levels of IL-27 were related to psoriasis area, severity index (PASI) score, and serum levels of IFNγ." (PMID 38566992, 2024). "While EBI3, as a component of the suppressive cytokines IL-35 and IL-27, is upregulated in acute inflammation, its expression decreases in chronic inflammatory diseases like psoriasis, allergic asthma, and allergic rhinitis." (PMID 31955243, 2020). "The heterodimeric IL-12 family member cytokines including, IL-12, IL-23, IL-27, and IL-35 and have multiple roles in regulating innate and adaptive immunity with crucial functions in inflammatory disorders such as psoriasis." (PMID 30989239, 2019). "This property of IL-27 has been proposed to be of significance for the inflammatory course of eczema and psoriasis." (PMID 22761702, 2012). "We seek to investigate how IL-27 interacts with the IFN system in inflammatory skin diseases such as psoriasis and lupus erythematosus in future studies." (PMID 22761702, 2012). "In addition, it has been found that the immunological effects of low levels of IL-27 in MS patients with psoriasis comorbidity have been suggested to be mitigated by the reverse impact of high levels of IL-27 generated by psoriasis." (PMID 38632254, 2024). "The administration of IL-27 into psoriasis mice reduced disease severity, showing less disease score and less acanthosis and dermal infiltrate of inflammatory cells, whereas the addition of anti-IL-27p28 antibody to psoriasis mice exacerbated skin inflammation." (PMID 38566992, 2024). "Differences in the role of IL-27 in IMQ-induced psoriasis mice may be attributed to several reasons." (PMID 38566992, 2024). "First, the finding of IL-27-inhibited psoriasis may correlate with the suppressive role of IL-27 in Th17 cells." (PMID 38566992, 2024). "Moreover, precautionary or therapeutic intracutaneous injection of IL-27 proteins significantly ameliorated the pathogenesis of psoriasis with dramatic inhibition of γδ T17 cells even though psoriatic γδ T cells had reduced expression of IL-27Ra." (PMID 38982043, 2024).
psoriasis (continued). "However, another study showed that IL-27+ skin cells were reduced in the psoriatic lesions, and there was lower expression of IL-27rα, IL-27p28, and gp130 in epidermis and dermis from patients with psoriasis." (PMID 38566992, 2024). "Furthermore, IL-27 was previously reported to promote the onset of psoriasis." (PMID 38940139, 2024). "By contrast, another study discussed the role of IL-27 in IMQ-induced psoriasis mice, showing worse clinical outcome, evidenced by severe scales, thicker skin, and more epidermal hyperplasia with elongation of rete ridges, and inflammatory cells infiltrate in IL-27 injected mice." (PMID 38566992, 2024). "Therefore, IL-27 may activate Th1-mediated response in psoriasis, such as regulating the expression of IFNγ, and may be involved in psoriasis development." (PMID 38566992, 2024). "Intracutaneous injection of IL-27 inhibited the production of IL-17 from γδ T cells and ameliorated the pathogenesis of IMQ-induced psoriasis-like cutaneous lesions." (PMID 38982043, 2024). "Psoriasis patients who were asymptomatic for SARS-COV-2 exhibited immune imbalance with high levels of IL-18, IL-17A and IL-6, and low levels of IL-27 compared to healthy controls." (PMID 34068473, 2021). "Psoriasis patients exhibit enhanced circulating levels of IL-6, IL-18, IL-17A, IFN-γ, TNF, IL-1β, IL-27 and IL-29." (PMID 34068473, 2021). "We also assessed functionality of the T cells by evaluating the secretion of several inflammatory cytokines (IL-17A, IFN-gamma, IL-2, IL-33, TNF-alpha, IL-21, IL-22, and IL-27), from cell-sorted purified CD4+ and CD8+ T cells isolated from lesional and unaffected skin biopsies of psoriasis patients." (PMID 23468834, 2013). "In addition, IL-27 binds to the IL-27 receptor and activates JAK-STAT signaling in macrophages, and MIP-2 has been reported to be upregulated in the skin of patients with psoriasis, a chronic inflammatory skin disease." (PMID 38543259, 2024). "In psoriasis, IL-27 can both be responsible for disease onset itself, inducing Th1 lymphocytes, and can suppress the inflammation when TNF-α is upregulated, suggesting that manipulation of IL-27 in psoriasis could be beneficent." (PMID 34068473, 2021).
inflammatory bowel disease (21 papers, 2013 to 2025). A spectrum of small and large bowel inflammatory diseases of unknown etiology. "Therefore, IL-27 has been investigated to treat the diseases caused by dysfunctions of immune systems in mucosa, such as nasal allergies and Inflammatory Bowel Disease." (PMID 35334059, 2022). "The mucosal administration of IL-27 was reported to exert beneficial effects in murine models of inflammatory bowel disease, through its capacity to modulate macrophage function that regulates T cell activation and IL-10 production." (PMID 40141330, 2025). "The studies showed that the level of IL-27 was increased in people with active inflammatory bowel diseases." (PMID 39766196, 2024). "Building on IL-27’s critical role in gut immunity, its regulatory mechanisms in chronic inflammatory diseases such as inflammatory bowel disease (IBD) have garnered significant attention." (PMID 39906735, 2024). "Mucosal delivery of IL-27 has been shown to have a therapeutic benefit in murine models of inflammatory bowel disease (IBD)." (PMID 37153622, 2023). "Recently, a potential marker (IL-27) has been proposed to distinguish between early-onset FPIES and NEC, and biomarkers for inflammatory bowel diseases are also currently being investigated in ongoing studies." (PMID 39275351, 2024).
Obesity (20 papers, 2015 to 2026). Accumulation of substantial excess body fat. "Supporting this, other studies indicate that reduced IL-27 levels are linked to hyperandrogenism, inflammation, and obesity-related conditions, such as polycystic ovary syndrome (PCOS)." (PMID 39906735, 2024). "Notably, the circulating level of IL-27 was uniquely reduced within inflammatory cytokines in obese human subjects, suggesting that IL-27 is an obesity-associated factor for BAT activity." (PMID 36674862, 2023). "Additionally, IL-27 has been demonstrated to suppress lipid accumulation in macrophages and modulate adipose tissue inflammation, indicating its potential in resolving the chronic inflammatory state associated with obesity." (PMID 39906735, 2024). "Most recently, scientists figured out IL-27-IL-27Rα signaling in protecting against DIO and ameliorating IR but whether IL-27 is associated with inflammation alleviation in CNS as the base of common characteristics of obesity and neuroinflammation still remains further explore." (PMID 35873818, 2022). "Firstly, a small sample population study was conducted to compare the disparities in serum 25(OH)D3 and IL-27 between individuals with obesity and healthy control groups." (PMID 41049367, 2025). "IL-27 has been identified as a key regulator of tissue thermogenesis, contributing to weight reduction and the inhibition of obesity." (PMID 39906735, 2024). "These coordinated actions of IL-27 from various sources collectively maintain normal gut immune function, reduce insulin resistance, and inhibit the progression of obesity." (PMID 39906735, 2024). "Understanding the structure and signaling pathways of IL-27 is essential for uncovering its potential effects on obesity-related metabolic diseases, particularly by examining its role in immune cells." (PMID 39906735, 2024). "This article provides a comprehensive review of the latest findings on IL-27 expression and signal transduction in the regulation of immune inflammatory cells, as well as its implications in obesity and other related metabolic diseases." (PMID 39906735, 2024). "A recent study showed that therapeutic administration of IL-27 protected against diet-induced obesity and glucose intolerance." (PMID 36674862, 2023). "IL-27 has an important metabolic function in humans and is a promising target for immunotherapy against obesity." (PMID 37510415, 2023). "The IL-27-IL-27Rα signaling pathway plays a key role in enhancing insulin resistance, promoting thermogenesis, and combating diet-induced obesity, which is a promising target for anti-obesity immunotherapy." (PMID 37600722, 2023). "IL-27 signaling promotes thermogenesis and energy expenditure, and protects mice from diet-induced obesity and insulin resistance." (PMID 35600577, 2022). "IL-27 is a heterodimeric cytokine that regulates the immune system, promotes adipocyte browning and thermogenesis to reduce obesity symptoms." (PMID 36698478, 2022). "IL-27, as a crucial immune regulatory factor, may significantly influence obesity-related inflammation and metabolic health through its effects on various immune cells." (PMID 39906735, 2024). "In addition, in the AD mice, exercise upregulated the IL27 genes, known for their role in regulating the immune system, promoting adipocyte thermogenesis and energy expenditure, reducing obesity, and ameliorating type 2 diabetes." (PMID 39408581, 2024). "Mechanistically, IL-27 activates the STAT3-mTOR signaling pathway in obese mice, promoting the synthesis and secretion of GLP-1 in the gut, thereby reducing insulin resistance and alleviating glucose and lipid metabolism disorders associated with obesity." (PMID 39906735, 2024). "Furthermore, it explores the potential of IL-27 as a novel therapeutic target for the treatment of obesity and metabolic disorders." (PMID 39906735, 2024). "However, concentrations of circulating IL-27 are reduced in human subjects with obesity (~700 pg/ml in lean vs. ~200 pg/ml in obese)." (PMID 37948192, 2023).
Obesity (continued). "The level of serum interleukin-27 (IL-27) was significantly decreased in the obesity group." (PMID 37600722, 2023). "Since activation of these pathways impacts inflammatory processes and/or lipolysis in WAT, obesity-induced IL-27 production in white adipocytes may contribute to metabolic dysregulation therein." (PMID 37948192, 2023). "Moreover, IL-27 was identified as a promising target for anti-obesity therapy, since it increases thermogenesis in white adipocytes thereby reducing body weight gain." (PMID 37948192, 2023). "However, the Cx3cr1+ macrophages are reportedly IL27 producers, where administration of IL27 protects against IR and obesity through its direct actions on Ucp1high adipocytes." (PMID 35211733, 2022). "Taken together, the results indicated that the protective effect of FAK on obesity may be related to the regulation of Leptin and IL-27." (PMID 36698478, 2022). "Conclusively, these findings demonstrated that FAK intervention can effectively improve obesity in mice caused by HFD and the potential mechanisms was related to the regulation of serum levels of leptin and IL-27, lipogenesis and lipolysis in adipose tissue and gut microbiota composition." (PMID 36698478, 2022). "Interestingly, IL-27 levels increase following weight loss, suggesting a negative correlation between IL-27 and obesity in humans." (PMID 39906735, 2024). "Additionally, elevated IL-27 levels may help prevent obesity by promoting uncoupling protein 1 (UCP1) production, enhancing adipocyte thermogenesis and energy expenditure in HFD-fed mice." (PMID 39765814, 2024). "Thus, IL-27 could be a promising target for the immunotherapy of obesity and metabolic morbidities in the future." (PMID 35600577, 2022). "Building on the findings from IL-6 and IL-10 studies, future research should explore whether IL-27 activates gut immune and endocrine pathways to promote GLP-1 secretion, thereby improving insulin resistance and alleviating glucose and lipid metabolism disorders associated with obesity." (PMID 39906735, 2024). "Herein, FAK dramatically increased the serum level of IL-27 in HFD-fed mice, suggesting the potential of promoting the burning of adipose tissue and fat oxidation in mice to ameliorate obesity." (PMID 36698478, 2022). "Amongst the factors that exhibited statistically significant differences between the lean and obese groups with obesity at T3 were myeloid factors, including CCL4, IL-1β, IL-1RA, and IL-27." (PMID 34195568, 2021). "BATF also alleviated HFD-induced obesity in mice, not by directly acting on adipose tissue but by influencing IL-27, which acts as a regulator of fat deposition." (PMID 37712938, 2023). "A recent study in the journal Nature found that IL-27 promotes the browning of adipose tissue by up-regulating the expression of Uncoupling Protein 1 (UCP1) to promote heat production and energy consumption, thereby reducing obesity." (PMID 35938165, 2022). "Interestingly, levels of plasma regulatory factors (IL1RA, PDGF, CCL22) were significantly elevated, whereas those of IL-27, which activates monocytes via the STAT1 signaling pathway, were lower in plasma of mothers with obesity at T3." (PMID 34195568, 2021).
parasitic infections (20 papers, 2014 to 2025). "Similar studies have reported lethal, exacerbated inflammation in IL-27-deficient mice in response to additional parasitic infections." (PMID 32802395, 2020). "IL27 has previously been implicated in immunity against viral, bacterial, and parasitic diseases and in many reported studies was essential for limiting immune pathology." (PMID 32547548, 2020). "In contrast to most bacterial-induced infections, parasitic infections caused by helminths and protozoa, which typically trigger Th2 immunity, have demonstrated different outcomes as a result of IL-27 blockade." (PMID 32802395, 2020). "The hydrodynamic injection of IL-27 expression vector into the infected IFN-γ-deficient mice showed significantly decreased parasitemia compared with that of control vector." (PMID 26991425, 2016). "IL-27, a heterodimer of p28 and EBI3 produced by APCs, IL-27 exhibits dual pro- and anti-inflammatory properties and promotes Th1 responses during bacterial and parasitic infections." (PMID 40519922, 2025). "The proportions of CD4+ T cells in peripheral blood (PB) were significantly higher at day 7 and 28 compared to wild‐type (WT) for Ebi3−/− mice and at day 21 for Il‐27−/− mice, although parasitemia levels were comparable." (PMID 37855243, 2023). "Neutralization of IL-27 in acutely infected BALB/c led to decreased parasite burdens and a transient increase in IFN-γ+ splenic T cells, while administration of IL-27 to C57BL/6 promoted parasite infection." (PMID 33680991, 2021). "Th1 cell formation is induced by IL-27 in the context of bacterial or parasitic infections." (PMID 41561993, 2025). "Collectively, results imply that, during bacterial or parasitic infections which act like strong polarizing stimuli, the ability of IL-27 to promote TH1-cell responses becomes secondary to its role as a suppressor of effector T-cell proliferation and cytokine production." (PMID 34996392, 2022). "Recently, IL-27 was described as a new important player during intracellular parasitic infections." (PMID 34869064, 2021). "Whereas the strong correlation of IL-27 with parasitemia could reflect enhancing effect on P. falciparum dissemination, it could also reflect a counteracting mechanism induced by the parasites." (PMID 31964363, 2020). "Here, we show that IL-27 derived from IFNγ responding dendritic cells (DCs) is crucial to drive the differentiation of a specialized Th1-Treg cell subset to limit IFNγ-mediated Th1 inflammation in a parasitic infection setting." (PMID 25658840, 2015). "In addition, the hydrodynamic injection of the IL-27 expression vector into infected IFN-γ-deficient mice greatly recovered the number of LSK cells and neutrophils in the BM and spleen and eventually reduced parasitemia." (PMID 26991425, 2016). "Serum levels of IL-6, IL-27, CCL3, CCL5, CXCL10, CCL11, and CCL17 in patients with different parasitic infection profiles living in the rural community of Brejo do Amparo, Januária, Minas Gerais, Brazil." (PMID 33777015, 2021). "By selectively inhibiting IL-27 during this parasitic infection, we discovered that IL-27 was only needed during, but not prior to, infection." (PMID 38376210, 2024). "IL-27 was strongly correlated with the degree of parasitemia with the same pattern in those with and those without co-infection with HIV." (PMID 31964363, 2020). "Thus, the blood stage of malaria infection augments the expression of IL-27 through IFN-γ, and IL-27 then promotes the expansion, differentiation, and mobilization of LSK cells into the spleen to control parasitemia." (PMID 26991425, 2016). "However, during the late phase of infection, WSX-1/IL-27 seems to play a role in limiting the production of pro-inflammatory cytokines such as IFN-γ, leading to augmented reduction of parasitemia, as in the case of infection with lethal P. berghei NK65." (PMID 26991425, 2016).